CDK5 (cyclin dependent kinase 5)
Diseases named in the same sentence as CDK5 in open-access papers (continued):
Sharing a sentence is not in itself a finding about the gene and the disease.
liver cancer (13 papers, 2016 to 2025). An epithelial or non-epithelial malignant neoplasm that arises from the liver. "To explore the specific molecular mechanism by which ATG9B-4 regulates CDK5, we performed mRNA sequencing of liver cancer cells overexpressing ATG9B-4." (PMID 40258750, 2025). "Lnc ATG9B-4 aggravated the progression of liver cancer by up-regulating cyclin-dependent-kinase 5 (CDK5)." (PMID 40258750, 2025). "Today the findings highlight the complex interplay between lnc ATG9B-4, ARNTL, and CDK5 in liver cancer." (PMID 40725041, 2025). "The results of OD value indicated that CDK5 knockdown effectively suppressed the proliferation of liver cancer cells induced by ATG9B-4." (PMID 40258750, 2025). "Apigenin has also been reported as an indirect activator of the PDR via cyclin-dependent kinase 5 (Cdk5) in human HepG2 liver cancer cells, however, the ability of the flavonoid to interact directly with the PXR has been ruled out." (PMID 36613834, 2022). "Dinaciclib, a CDK5 inhibitor, is in a preclinical trial for the treatment of multiple types of cancer, including liver cancer, thyroid cancer, and chronic lymphocytic leukemia." (PMID 31718704, 2019). "Finally, loss of CDK5 abrogated the promotion of proliferation and migration by ATG9B-4 in liver cancer cells." (PMID 40258750, 2025). "ARNTL negatively regulatse CDK5 expression in liver cancer cells." (PMID 40258750, 2025). "ARNTL could downregulate CDK5 expression in liver cancer cells." (PMID 40725041, 2025). "CDK5 knockdown partially attenuated the ATG9B-4-induced increase in proliferation and migration in liver cancer cells." (PMID 40258750, 2025). "The overexpression of ATG9B-4 in liver cancer cells, leading to a downregulation of ARNTL and an upregulation of CDK5." (PMID 40725041, 2025). "Our results suggested that the expression of CDK5 decreased in ARNTL-overexpressing liver cancer cells but that the overexpression of CDK5 did not affect ARNTL expression." (PMID 40258750, 2025). "Our previous studies showed that ATG9B-4 indirectly up-regulated the expression of CDK5, and this study showed that ATG9B-4 could downregulate ARNTL expression in liver cancer cells." (PMID 40258750, 2025). "Liver cancer cells were transfected with ATG9B-4, ARNTL, or si-CDK5." (PMID 40258750, 2025). "Flavopiridol is an inhibitor of cyclin-dependent kinases (CDKs) (including CDK1, CDK2, CDK4, CDK5, CDK6, CDK7, CDK8, and CDK9) and has been investigated for the treatment of several types of cancers, including leukemia, liver cancer, and renal cancer, in clinical phase 2 trials (24, –, 26)." (PMID 31822599, 2019). "Furthermore, from the meta-analysis results of TCGA and other open databases, CDK5 expression in HCC was significantly increased compared with non-HCC liver cancer." (PMID 29312535, 2017).
lung adenocarcinoma (12 papers, 2013 to 2024). A carcinoma that arises from the lung and is characterized by the presence of malignant glandular epithelial cells. "This study highlights CDK5 as a potential therapeutic target, in combination with immunotherapy, for advanced lung adenocarcinoma." (PMID 38474186, 2024). "Accordingly, concomitant pharmacological inhibition of ERK5 and CDK5 in a mouse model of KrasG12D-driven lung adenocarcinoma suppressed tumor progression and promoted cancer cell death." (PMID 39271958, 2024). "TTN-AS1 sponges miR-142-5p to modulate CDK5, triggering the growth and metastasis of lung adenocarcinoma." (PMID 34141611, 2021). "For illustration, TTN-AS1 with high expression in lung adenocarcinoma cells can expedite cellular functions of lung adenocarcinoma through serving as a sponge of miR-142-5p to regulate CDK5." (PMID 32863773, 2020). "CDK5 inhibition improves antitumor immunity in lung adenocarcinoma." (PMID 38638430, 2024). "Based on the activity of these CDK inhibitors, we speculated that CDK2, CDK4/6, and CDK5 are candidates that activate DRP1 during the cell cycle in lung adenocarcinoma cell lines." (PMID 33152171, 2021). "Combined genetic or pharmacological inhibition of ERK5 and CDK5 triggered ROS-induced DNA damage and apoptosis in cancer cells and mouse models of KRAS-driven lung adenocarcinoma, recapitulating FAK pharmacological inhibition." (PMID 39271958, 2024). "Inhibition of CDK5 reduced PD-L1 levels via the ubiquitination-proteasome pathway by TRIM21 and improved antitumor immunity in lung adenocarcinoma." (PMID 38638430, 2024). "In lung adenocarcinoma, TTN-AS1 expression is also remarkably up-regulated and TTN-AS1 can sponge miR-142-5p to increase CDK5 expression, thus facilitating cell migration, invasion and EMT." (PMID 33517826, 2021).
medulloblastoma (12 papers, 2015 to 2025). A malignant, invasive embryonal neoplasm arising from the cerebellum. "Studies in medulloblastoma showed that loss of CDK5 leads to sustained expression of PD-L1 transcriptional repressors, resulting in reduced PD-L1 levels on tumor cells." (PMID 41561738, 2025). "A recent study reported that IFNγ-associated PD-L1 upregulation in medulloblastoma is mediated by CDK5, the depletion of which downregulates PD-L1 in malignant cells." (PMID 34479614, 2021). "Cdk5 promotes immune evasion of medulloblastoma by upregulating PD-L1 expression, and blocking Cdk5 enhances immune sensitivity." (PMID 34814918, 2021). "Cyclin-dependent kinase 5 (Cdk5) function allows some tumor models as medulloblastoma (MB) to evade immune elimination via INF-g-induced PD-L1 up-regulation." (PMID 35582274, 2019). "Experimentally, they showed that IFN-γ-induced programmed death ligand 1 (PD-L1) upregulation on medulloblastoma cells requires Cdk5." (PMID 31614664, 2019). "In a study of medulloblastoma, depletion of Cdk5 led to the upregulation of interferon regulatory factor 2 and interferon regulatory factor binding protein 2, which in turn, suppressed the expression of PD-L1." (PMID 29765155, 2018). "Prior studies have shown that CDK5 enhances PD-L1 expression in medulloblastoma, and we have previously demonstrated that genetic knockdown of CDK5 or pharmacological inhibition with Roscovitine increases proteasomal degradation of PD-L1 leading to a reduction in PD-L1 expression in NSCLC." (PMID 41561738, 2025). "Finally, in medulloblastoma, CDK5 was reported to help the cancer evade immune elimination by up-regulating the interferon-γ-induced PD-L1 expression." (PMID 32708903, 2020). "Cyclin‐dependent kinase 5 (CDK5) has been shown to increase the expression of PD‐L1 in NSCLC and medulloblastoma." (PMID 39153212, 2024). "Given that Paullones, including alsterpaullone, have been identified as CDK1/CDK2/CDK5 and GSK3B inhibitors, we examined the gene expression profiles of the CDK genes in the Group 3 medulloblastoma cell lines." (PMID 26061748, 2015). "As CDK5 downregulates FBXO22, which in turn increases PD-L1 levels in NSCLC, this mechanism may also occur in medulloblastoma." (PMID 37993880, 2023). "Cdk5 was thus necessary for PD-L1 upregulation after IFN-γ stimulation through STA1/IRF1 axis and its disruption led to tumor rejection in a CD4 + T-cell-dependent manner in medulloblastoma mouse models." (PMID 29765155, 2018).
multiple myeloma (12 papers, 2015 to 2023). "In ovarian cancer, multiple myeloma (MM), and head and neck cancer, only CDK5 upregulation has been reported." (PMID 37993880, 2023). "EphA4 engages with cyclin-dependent kinase 5 (CDK5) in multiple myeloma (MM) and increases its expression, and facilitates bortezomib resistance by increasing Akt phosphorylation." (PMID 36830852, 2023). "Silencing CDK5 has been demonstrated to sensitize MM cells to treatment with bortezomib and CDK5 inhibitors, such as seliciclib and dinaciclib, have been shown to enhance bortezomib-induced cytotoxicity in myeloma cells." (PMID 27655636, 2016). "In multiple myeloma, downregulated expression of cdk5 predicted favorable overall survival after bortezomib treatment." (PMID 26860827, 2016). "CDK5 knockdown suppresses the viability of MM cells and sensitizes them to bortezomib, a proteasome inhibitor that generates considerable clinical response in newly diagnosed as well as advanced multiple myeloma patients." (PMID 37993880, 2023). "The level of CDK5 expression predicts the survival of relapsed multiple myeloma patients." (PMID 25625291, 2015). "Moreover, downregulation of CDK5 indicated higher overall survival in multiple myeloma." (PMID 26860827, 2016). "Moreover, CDK5 can be used to predict the prognosis of multiple myeloma." (PMID 26860827, 2016). "EphA4 binds CDK5 and increases its expression, leading to enhanced AKT activation and cell adhesion-mediated drug resistance in multiple myeloma." (PMID 37993880, 2023). "Moreover significant upregulation of CDK5 expression has been reported in colorectal, head/neck, breast, lung, ovarian, lymphoma, prostate, sarcoma, myeloma and bladder cancers, and there is well documented evidence that it plays a role in these cancers as well as lymphoma and multiple myeloma." (PMID 25625291, 2015).
Anxiety (11 papers, 2013 to 2025). Intense feelings of nervousness, tension, or panic often arise in response to interpersonal stresses. "Other studies have implicated Cdk5 activity in the septum in regulating anxiety-like behaviors in animals." (PMID 35645825, 2022). "Cdk5 conditional knockout mice display reduced anxiety-like behaviors and enhanced cocaine locomotor sensitization." (PMID 35645825, 2022). "This provides a promising landscape for future studies to assess the effects of brain-permeable Cdk5 inhibitors to combat stress, anxiety, depression, addiction, cancer, and neurodegeneration." (PMID 35645825, 2022). "Here the authors establish a critical role for mPFC in regulating pain sensation and pain-related anxiety, mediated by activation of the cyclin-dependent kinase 5 signalling pathway." (PMID 26179626, 2015). "Our findings implicate Cdk5/p35 in spatial learning and memory, anxiety-like behavior, LTD induction, and the maintenance of spine density on hippocampal CA1 pyramidal neurons." (PMID 25404232, 2014). "For instance, while Pdyn is the only gene positively correlated with anxiety-like behavior in XX mice, Htr1a, Cdk5, Adcy2, Akt1, Akt2, and Akt3 positively correlate with anxiety-like behavior in XY- mice." (PMID 24199867, 2013). "To test whether Cdk5 is involved in the modulation of pain sensation and pain-related anxiety-like behaviours, we first examined Cdk5 and p-Cdk5 protein levels in the contralateral and ipsilateral PL, CG1 or IL 1 or 7 days after CFA injection." (PMID 26179626, 2015). "In addition, these changes in synaptic ultrastructure might lead to ablation of cyclin-dependent kinase 5, a major regulator of synaptic plasticity, which could also enhance the release of gamma aminobutyric acid and decrease anxiety." (PMID 29896126, 2018). "Our findings are supported by the recent study reporting that mice in which the Cdk5 phosphorylation sites are mutated into unphosphorylatable ones show increased BDNF transport and release associated with enhanced hippocampal neurogenesis and a decrease of anxiety-like behaviors." (PMID 24019939, 2013).
atherosclerosis (11 papers, 2014 to 2024). A disease characterized by the build-up of fatty material and calcium deposition in the arterial wall resulting in partial or complete occlusion of the arterial lumen. "In the Chr 5 locus, there are 4 hepatic genes with eQTL that are in strong LD with the atherosclerosis associated SNP at the locus: Nub1 (p = 1.65×10−16), Nos3, (p = 3.08×10−6), Cdk5 (p = 2.48×10−5), and Abcb8 (p = 7.46×10−4)." (PMID 26694027, 2015). "A truncated regulatory subunit of Cdk5 is accumulated in the atherosclerotic areas of aortas, whereas the inhibition of Cdk5 not only attenuates the expression of inflammatory genes in endothelial cells, but also suppresses the development of atherosclerosis in apolipoprotein E-deficient mice." (PMID 33291667, 2020). "Furthermore, cyclin-dependent kinase 5-mediated hyperphosphorylation promotes the development of age-related endothelial senescence and atherosclerosis." (PMID 39519833, 2024). "Additionally, cyclin-dependent kinase 5 (CDK5)-mediated hyperphosphorylation of Sirt1 at Ser47 con-tributes to the development of endothelial senescence and atherosclerosis." (PMID 27744418, 2016). "For example, phosphorylation at S273 by cyclin-dependent kinase 5 (CDK5) has been shown to increase proinflammatory factors including TNF-α, IL-1β, and foam cell formation, which worsen atherosclerosis." (PMID 37833942, 2023). "The inhibition of foam cell formation by macrophages was based on the suppression of cyclin-dependent kinase 5 (Cdk5)/CD36 pathway, a pathway that has been correlated with LPS-induced inflammation and advanced glycation end products (AGEs)-derived atherosclerosis." (PMID 36834796, 2023). "Moreover, it has been reported that miR-188 inhibits cyclin-dependent kinase 5 (CDK5) gene expression, which is a strong regulator of sirtuin 1 (SIRT1), which acts on cellular senescence and the development of atherosclerosis." (PMID 32903262, 2020).
cognitive decline (11 papers, 2011 to 2025). "The study not only contributes to our understanding of the molecular mechanisms underlying T2D-associated neurodegeneration but also positions Cdk5 inhibition as a compelling strategy for mitigating the complex interplay between metabolic disorders and cognitive decline." (PMID 40224020, 2025). "Numerous studies have revealed that Cdk5 is involved in the regulation of synaptic plasticity and deregulation of its kinase activity contributes to synaptic loss and dysfunction, resulting in neuronal network impairment and cognitive decline in AD." (PMID 25875370, 2015). "Genetic deletion of Cdk5 in mice attenuates memory and learning deficits signifying involvement of Cdk5 in the development and progression of cognitive decline in HD." (PMID 38842132, 2024). "The use of Cdk5 inhibitory peptide has been shown to reduce the effects of increased activation of Cdk5/p25 in mice, exhibiting decreased neuroinflammation, brain atrophy and cognitive decline." (PMID 26578864, 2015). "Our research identifies Cdk5 as a key link between T2D and cognitive decline." (PMID 40224020, 2025). "We also elucidated the underlying molecular machinery by demonstrating a physical interaction between 5-HT7R and CDK5 leading to receptor-dependent CDK5 activation, which induced aberrant Tau hyperphosphorylation, aggregation and neuronal death, finally resulting in cognitive decline." (PMID 38641599, 2024). "In contrast, the regulation of Aβ through CDK5, calmodulin phosphatase signaling, and increased synaptic vesicle cycling in the AD state disrupts synaptic function and homeostasis, ultimately leading to cognitive decline and neurodegeneration." (PMID 38516314, 2024). "Previous research, including our work, has highlighted the hyperactivation of CDK5 and the generation of p25 in HFD mouse models of T2D, coinciding with cognitive decline." (PMID 40224020, 2025).
medullary thyroid carcinoma (10 papers, 2015 to 2023). "Suppressing both STAT3 and CDK5 has been shown to slow down human medullary thyroid cancer cell proliferation." (PMID 37046823, 2023). "CDK5R1 is one of the activators of CDK5, which binds and activates CDK5 to drive G1-S transition and RB phosphorylation in medullary thyroid carcinoma models." (PMID 38093298, 2023). "Protein interaction between RET and CDK5 was further confirmed by evaluating their co-localization in human medullary thyroid cancer cells." (PMID 34207842, 2021). "CDK5 inhibition remarkably reduces cell viability and cell proliferation in human medullary thyroid cancer." (PMID 34207842, 2021). "Here, we investigated RET activation and its biochemically interaction with CDK5 in GDNF-induced medullary thyroid cancer proliferation." (PMID 34207842, 2021). "Regarding the active role of CDK5 in cancer progression, we have previously identified the cumulative roles of CDK5 in neuroendocrine cancers, including medullary thyroid cancer." (PMID 34207842, 2021). "In conclusion, our study reveals that CDK5 plays an essential role in regulating GDNF-induced human medullary thyroid cancer cell proliferation." (PMID 34207842, 2021). "In other studies, CDK5 promoted medullary thyroid carcinoma cell growth by regulating STAT3 activation and cell proliferation." (PMID 29312535, 2017). "In medullary thyroid carcinoma, CDK5 is essential to tumorigenesis and progression by retinoblastoma protein (Rb) and inhibition of Rb reduced proliferation of medullary thyroid carcinoma." (PMID 26860827, 2016). "In addition to the activation of RET and STAT3, it has been noted that CDK5 regulates STAT3 in medullary thyroid cancer, influencing cell proliferation." (PMID 37046823, 2023). "Since our current data also showed that GDNF enhanced p35/CDK5 activity in TT cell, therefore, we investigated similar signaling pathways that might be related to CDK5 activation in medullary thyroid cancer cell proliferation." (PMID 34207842, 2021). "Interestingly, we identified for the first time that CDK5 physically interacts with RET protein in GDNF-induced medullary thyroid cancer cell proliferation." (PMID 34207842, 2021). "Overall, our results provide a new mechanism for medullary thyroid cancer cell proliferation, suggesting that targeting CDK5 may be a promising therapeutic candidate for human medullary thyroid cancer in the near future." (PMID 34207842, 2021). "Regulation of CDK5 activity promoted the proliferation of medullary thyroid carcinoma (MTC)." (PMID 29312535, 2017). "Therefore, targeting of CDK5 might be a therapeutic approach for the treatment of human medullary thyroid cancer in the near future." (PMID 34207842, 2021). "However, the role of CDK5 in GDNF-induced RET signaling in medullary thyroid cancer proliferation remains unknown." (PMID 34207842, 2021). "Besides, the inhibition of CDK5 either via shRNA or by its pharmacological inhibitor roscovitine could reduce the migration and growth of medullary thyroid carcinoma cells in vitro." (PMID 27406233, 2016). "We first investigated the expression level of CDK5 and RET proteins in anaplastic thyroid cancer ARO, follicular thyroid cancer WRO, papillary thyroid cancer Cg3, and medullary thyroid cancer cells TT." (PMID 34207842, 2021). "In the model of mice infected with medullary thyroid carcinoma (MTC), overexpression of p25 led to excessive CDK5 activity and the development of malignant MTC." (PMID 33805800, 2021). "We first investigated the expression of CDK5 and p35 in anaplastic thyroid cancer ARO, follicular thyroid cancer WRO, papillary thyroid cancer Cg3, and medullary thyroid cancer cells TT." (PMID 34207842, 2021). "Furthermore, our previous findings have demonstrated that CDK5 regulates STAT3 activation in the medullary thyroid cancer cell proliferation, and inhibition of STAT3 as well as CDK5 decelerates human medullary thyroid cancer cell proliferation." (PMID 34207842, 2021).